NLRP3 (NLR family pyrin domain containing 3)
Diseases named in the same sentence as NLRP3 in open-access papers (continued):
Sharing a sentence is not in itself a finding about the gene and the disease.
periodontitis (continued). "Together, these preventive and therapeutic strategies highlight the feasibility of locally modulating NLRP3 activity to manage periodontitis, peri-implantitis, and other oral inflammatory conditions." (PMID 41596738, 2026). "Although the NLRP3 inflammasome is well recognized for promoting osteoclastogenesis in infection-induced periodontitis, recent evidence suggests a more context-dependent role." (PMID 41596738, 2026). "Based on our results, we propose a model where, in wild-type (WT) macrophages, LPS (periodontitis scenario) increases NLRP3 activation, driving ROS production." (PMID 40490723, 2025). "The NLRP3 inflammasome is a key innate immune complex that drives IL-1 family cytokine production in periodontitis." (PMID 41322905, 2025). "A multitude of studies has demonstrated the pivotal role of the ROS/NLRP3 inflammasome in the development and progression of periodontitis." (PMID 41298339, 2025). "Future studies should explore the potential of antioxidants not only as ROS scavengers but also as modulators of NLRP3 activation, aiming to mitigate both inflammation and OS in periodontitis." (PMID 41298339, 2025). "Salivary exosomal miR-223-3p is significantly downregulated in periodontitis and plays a key role in suppressing pyroptosis, a programmed cell death process, in macrophages by targeting the NLRP3-caspase-1-GSDMD signaling axis." (PMID 41322905, 2025). "In this context, studies have reported a high expression of the NLRP3 inflammasome, both in the gingival tissues of patients with periodontitis, as well as in cells of the innate immune system and pancreatic β-cells in patients with T2DM." (PMID 40406515, 2025). "In fact, different studies have reported increased mRNA and protein levels of NLRP3 in gingival tissues and saliva from patients with PD, especially those with periodontitis, suggesting there is local priming of the NLRP3 inflammasome in PD." (PMID 40427389, 2025). "Meanwhile, DUBs, including OTUD1, A20, CYLD, UCH‐L1 and USPs, also broadly modulate periodontitis progression by regulating signalling pathways such as NF‐κB, Wnt/β‐catenin, NLRP3, and BMP2." (PMID 39626954, 2025). "Recent studies have highlighted the role of the ROS/TXNIP/NLRP3 pathway in periodontitis development." (PMID 41298339, 2025). "In conclusion, A20 attenuated periodontitis progression by suppressing NLRP3‐mediated M1 macrophage polarisation, suggesting the potential of A20 as a novel therapeutic target for periodontitis management." (PMID 39626954, 2025). "The identification of the NLRP3 inflammasome offers a key regulatory pathway for investigating periodontitis." (PMID 41298339, 2025). "In this review, the regulatory role of exosomal miR-223-3p in periodontitis was also highlighted, specifically its ability to suppress NLRP3 inflammasome-mediated pyroptosis and the release of pro-inflammatory cytokines such as IL-1β and IL-6 in macrophages." (PMID 41322905, 2025). "In this context, several studies have reported elevated expression of the NLRP3 inflammasome, both in the gingival tissues of patients with periodontitis and in cells of the innate immune system and pancreatic β-cells in patients with T2DM." (PMID 41009326, 2025). "Our findings complement previous local-focused studies reporting higher levels of NLRP3 in the gingival tissue of periodontitis patients." (PMID 40427389, 2025). "Shared genetic risk factors between periodontitis and Alzheimer’s have also been proposed, such as polymorphisms in genes related to innate immunity and inflammatory response (e.g., TLR4, NLRP3, TREM2)." (PMID 40231144, 2025). "ROS generation in response to LPS is a crucial signal in the inflammatory process, and ROS also trigger NLRP3 inflammasome activation, contributing to periodontitis progression." (PMID 41298339, 2025). "Patients with periodontitis have been observed to have significantly higher levels of NLRP3, both in blood and saliva." (PMID 41009326, 2025).
periodontitis (continued). "Local increases in NLRP3 during periodontitis likely contribute to its entry into the systemic circulation, promoting systemic inflammation." (PMID 40572711, 2025). "This study demonstrates that bacterial and metallic components drive the activation of both NLRP3 and AIM2 inflammasomes in macrophages, highlighting their roles in the inflammatory responses associated with periodontitis and peri-implantitis." (PMID 40490723, 2025). "As evidence of the systemic impact of periodontitis, we can discuss the correlation between serum NLRP3 levels and the presence of periodontitis." (PMID 40572711, 2025). "Accumulating evidence bestows NLRP3 inflammasome activation a central role in the pathogenesis of PD, especially periodontitis." (PMID 40427389, 2025). "It is suggested that EGCG plays anti‐inflammatory and antioxidative roles by simultaneously regulating the expression of HDAC6 and the Nrf2/HO‐1/NLRP3 signal axis in the present periodontitis cell model." (PMID 40289388, 2025). "The expression of NLRP3, NLRP2, IL-1β, and IL-18 in gingival tissues from patients with gingivitis, chronic periodontitis, and aggressive periodontitis was upregulated, with positive correlations observed between NLRP3 and its downstream products." (PMID 41440367, 2025). "In gingival tissues, the expression levels of NLRP3, Caspase‐1, and IL‐1β were significantly higher in patients with periodontitis than in healthy individuals." (PMID 41298339, 2025). "It has been observed that patients with periodontitis exhibit significantly higher levels of NLRP3, in both blood and saliva." (PMID 40406515, 2025). "Yunvjian decoction attenuates LPS-induced periodontitis in alveolar bone by suppressing the NLRP3 pathway." (PMID 40305201, 2025). "Studies have shown that the NLRP3 inhibitor MCC950 significantly alleviates ligature-induced periodontitis, reduces IL-1β activation and osteoclast differentiation, and thereby inhibits alveolar bone resorption." (PMID 41415576, 2025). "The NLRP3 inflammasome can also be activated by ROS and plays a key role in inflammatory diseases including periodontitis." (PMID 39456522, 2024). "Despite these findings, studies specifically addressing the O-GlcNAcylation of NLRP3 have primarily focused on periodontitis and non-alcoholic fatty liver disease." (PMID 39742284, 2024). "Recent studies have shown that activation of Nucleotide Binding Oligomerization Domain, Leucine Rich Repeat and Pyrin Domain Containing Protein 3 (NLRP3) contributes to local and systemic inflammation in both periodontitis and acute coronary syndrome (ACS)." (PMID 38451305, 2024). "A study conducted in 2014 demonstrated a strong correlation between NLRP3 and advanced periodontitis." (PMID 38391885, 2024). "In a recent study, patients with chronic hepatitis C and periodontitis were found with significantly more elevated levels of NLRP3, caspase-1, and IL-18 in GCF samples, than systemic healthy patients with periodontitis." (PMID 38817019, 2024). "Recent studies have highlighted the roles of galectin-3, Nod-like receptor pyrin domain-containing protein-3 (NLRP3), and soluble urokinase-type plasminogen activator receptor (suPAR) in periodontitis progression and their interactions with CRP." (PMID 39453923, 2024). "Recent research has investigated how O-GlcNAcylation of NLRP3 contributes to pyroptosis induced by LPS in primary human gingival fibroblasts (HGFs), aiming to elucidate the pathogenesis of periodontitis." (PMID 39742284, 2024). "The NLRP3 inflammasome has been the major target of studies focusing on the role of macrophages in many inflammatory diseases including periodontitis." (PMID 38817019, 2024). "Evidence suggests that NLRP3 inflammasome activation leads to M1 macrophage polarization in inflammatory root resorption and periodontitis." (PMID 38817019, 2024).
periodontitis (continued). "AZGP1 participates in the pathogenesis of periodontitis by aggravating macrophage M1 polarization and pyroptosis through the NLRP3/caspase-1 pathway.signaling pathway." (PMID 38800469, 2024). "Conversely, periodontal therapy contributed to decreasing of the NLRP3 levels in GCF samples of chronic periodontitis patients." (PMID 38817019, 2024). "Histological analyses of mouse periodontitis models confirmed the expression of NLRP3 as well as GSDMD was downregulated in CKO mice." (PMID 38696610, 2024). "Recent studies regarding Galectin-3, NLRP3, and suPAR have provided clues on the synergistic effect in periodontitis evolution and inflammation." (PMID 39453923, 2024). "Individuals with chronic or aggressive periodontitis show elevated NLRP3 expression levels in gingival tissue compared to healthy controls." (PMID 38460073, 2024). "This research indicates that caspase-1, activated by the NLRP3 inflammasome, contributes to the development of periodontitis by inducing cell pyroptosis." (PMID 39742284, 2024). "Despite Dioscin being confirmed as an inhibitor of the NLRP3 inflammasome 17, 20, literature on the role of Dioscin in managing periodontitis remains scarce." (PMID 38385066, 2024). "According to the study, mice with periodontitis exhibit an increase in NLRP3 inflammasome expression, and inhibit the activation of the NLRP3 inflammasome will alleviate the occurrence of periodontitis." (PMID 38191432, 2024). "Periodontitis and their biomarkers galectin 3 and NLRP3 are related with halitosis in very recent literature." (PMID 38954692, 2024). "In another study, salivary levels of NLRP3 were found significantly higher in chronic periodontitis patients as compared to healthy controls." (PMID 38817019, 2024). "NLRP3, a key component of the inflammasome, contributes to the chronic inflammatory facet of periodontitis by mediating immune cell recruitment, cytokine production, and tissue destruction." (PMID 39453923, 2024). "IL-37 prevents the progression of periodontitis by suppressing NLRP3 inflammasome activation and mediating M1/M2 macrophage polarization." (PMID 38800469, 2024). "A clinical report showed that periodontitis patients have higher levels of NLRP3, ASC, caspase 1 and IL-1β in serum and saliva than healthy controls." (PMID 38596842, 2024). "In 2009, it was demonstrated that NLRP3 and NLRP2 presented increased levels in affected periodontal tissues, compared with healthy tissues, confirming the involvement of the NLRP3 inflammasome in the pathogenesis of periodontitis." (PMID 38391885, 2024). "NLRP3 inflammasome activation has also been reported to accelerate the progression of chronic inflammatory diseases, such as periodontitis, characterized by exacerbating the absorption of alveolar bone." (PMID 37051938, 2023). "When compared to healthy controls, patients with chronic periodontitis had salivary levels of NLRP3, ASC, and IL-1β that were 2.94 times higher, 1.70 times higher, and 1.53 times higher, respectively." (PMID 36769328, 2023). "The C-T genotype among periodontitis was significantly different from controls, while the C-C genotype among control was significantly different from periodontitis at NLRP3 rs10925024." (PMID 36812929, 2023). "More research will be needed to evaluate NLRP3's contribution to periodontitis in addition to other genetic, pathological, and environmental risk factors because of its complicated regulatory system." (PMID 36812929, 2023). "Existing studies indicate that the NLRP3/IL-1β signaling pathway played a crucial role in the occurrence and development of periodontitis." (PMID 37900318, 2023). "Recent research has shown that leptin can promote the progression of periodontitis by inducing pro-inflammatory M1 macrophage skewing through the leptin/NLRP3 signaling pathway." (PMID 37798684, 2023). "Meanwhile, overexpression of NLRP3 in gingival tissue and increased NLRP3 salivary levels have been observed in patients with periodontitis." (PMID 35083332, 2022).
periodontitis (continued). "Another aging-related model of periodontitis also suggested that NLRP3 played an inevitable role in osteoclastogenesis during aging." (PMID 36185327, 2022). "While in the study of periodontitis, glyburide can prevent NLRP3 inflammasome activation and decrease IL-1β release in periodontal pathogen-induced inflammation." (PMID 36185327, 2022). "We propose here NLRP3 as a regulator of neutrophil function, since its expression and activation regulate their accumulation in periodontitis resulting in a net beneficial effect on bone resorption suggesting a potential to modulate osteoclast activities." (PMID 35281020, 2022). "The inhibition of NLRP3 inflammasome in periodontitis is also documented as a mechanism of immune evasion." (PMID 35844512, 2022). "Processing of proinflammatory cytokine IL-1β is regulated by nucleotide-binding oligomerization domain-like receptor protein 3 (NLRP3) inflammasome complex, and NLRP3 expression is upregulated in the gingival tissue of patients with periodontitis." (PMID 36319994, 2022). "The presence of periodontitis was a strong predictor of increased NLRP3 ‘s serum and salivary concentrations." (PMID 35521636, 2022). "In this review, we describe the recent progress and our current understanding of NLRP3 inflammasome pathogenesis in periodontitis." (PMID 36185327, 2022). "Among all the pyroptosis-related inflammasomes and caspases, NLRP3 and caspase-1 are the most comprehensively characterized members in periodontitis." (PMID 36093182, 2022). "In inflammatory bone diseases such as periodontitis, the nucleotide-binding oligomerization domain, leucine-rich repeat, and pyrin domain-containing 3 (NLRP3) inflammasome accelerates bone resorption by promoting proinflammatory cytokine IL-1β production." (PMID 35682777, 2022). "Then we elucidate the development status of NLRP3 inflammasome inhibitors and show their application potential for treating periodontitis." (PMID 36185327, 2022). "In a model of tooth ligature-induced periodontitis, Nlrp3−/− mice or mice treated with MCC950 had reduced alveolar bone loss measured by μCT compared to control mice and reduced in vitro osteoclast differentiation." (PMID 35567665, 2022). "A recent clinical study reported that patients with periodontitis show elevated serum and saliva NLRP3 concentrations, and elevated NLRP3, ASC, and IL-1β concentrations in saliva are proposed biomarkers for periodontal clinical status." (PMID 35567665, 2022). "The activation of NLRP3 inflammasome has been found in periodontal tissues of periodontitis patients." (PMID 36185327, 2022). "In this review, we mainly focus on the negative regulation of NLRP3 inflammasome in periodontitis and highlight the importance of NLRP3 inflammasome as a candidate therapeutic target in periodontitis treatment." (PMID 36185327, 2022). "P. gingivalis therefore reveals a pathologic activity of NLRP3 on alveolar bone resorption during periodontitis." (PMID 35281020, 2022). "Our study sheds new light on the role of NLRP3 in periodontitis by highlighting the ambiguous role of neutrophils, and P. gingivalis which affects NLRP3 functions." (PMID 35281020, 2022). "In summary, this review reveals the recent progress and perspectives of NLRP3 inflammasome and the therapeutic potential of NLRP3 inflammasome inhibitors in periodontitis." (PMID 36185327, 2022). "Previous studies have shown that hypoxia is involved in NLRP3 activation and subsequent inflammasome formation by increasing TXNIP expression, and the occurrence of periodontitis is associated with the NRLP3 inflammasome." (PMID 35083332, 2022). "In humans, single-nucleotide polymorphisms of the IL1B gene increase susceptibility to periodontitis, and gingival tissues from periodontitis patients show elevated mRNA expression of NLRP3 and IL1B genes." (PMID 35567665, 2022). "In conclusion, this study was the first to prove that MARK4 affects the NLRP3 inflammasome-dependent pyroptosis in periodontitis." (PMID 34992737, 2022).
periodontitis (continued). "These indicate the participation of NLRP3 inflammasome in periodontitis by regulating diverse types of leukocytes." (PMID 36185327, 2022). "Immunohistochemistry confirmed, particularly in the periodontal epithelium layer, that the overall intensity of NLRP3 expression was higher in chronic periodontitis and patients with generalised aggressive periodontitis compared to healthy control subjects." (PMID 35008798, 2021). "To explore the role of NLRP3 in periodontitis, we used a classic periodontitis model, ligature‐induced periodontitis." (PMID 33382502, 2021). "This study is the first explorative approach evaluating NLRP3 (rs4612666) and CARD8 (rs2043211) polymorphisms in dental plaque and blood of periodontitis patients with coronary heart disease." (PMID 34199122, 2021). "The reported intensity of NLRP3 expression was statistically significantly higher in tissues from patients with periodontitis than that from healthy controls." (PMID 34869060, 2021). "The increased proportion of CD11b+ NLRP3+ macrophages in gingival tissue in periodontitis suggested their crucial role in the pathology of periodontitis." (PMID 34566966, 2021). "Consistent results also observed in human tissue, a research shows NLRP3 and IL‐1β have been found highly expressed in human gingival tissues with severe chronic periodontitis." (PMID 33382502, 2021). "Inflammasomes are activated and modulated by different metabolic alterations, and it has been reported that P. gingivalis infection induces an overexpression of PRRs and NLRP3 in T2DM-periodontitis patients, along with caspase-1 and IL-1β." (PMID 34572060, 2021). "There are several reports pointing to the roles of IL-6 and nod-like receptor family pyrin domain-containing protein-3 (NLRP3), as a component of the innate immune system, in the pathogenesis of periodontitis." (PMID 34645448, 2021). "In conclusion, the periodontitis-related bacteria (P. gingivalis and F. nucleatum) can initiate the overexpressed NLRP3, activate upstream signal molecules of ATR-CHK1, and inhibit the activation of CHK1, promoting tumor growth and proliferation." (PMID 34660289, 2021). "In this study, we used ligature‐induced periodontitis models of NLRP3 knockout mice (NLRP3KO) and their wildtype (WT) littermates to compare their alveolar bone phenotypes." (PMID 33382502, 2021). "We used ligature‐induced periodontitis models of NLRP3 knockout mice (NLRP3KO) and their wildtype (WT) littermates to compare their alveolar bone phenotypes." (PMID 33382502, 2021). "It has been found that the mRNA expression of NLR family pyrin domain-containing 3 (NLRP3) and IL-1β is increased in patients with periodontitis." (PMID 34356813, 2021). "NLRP3 inflammasome activation was detected in P. gingivalis-induced periodontitis, leading to upregulation of IL-1β and IL-18 and enhancement of bone resorption." (PMID 34177950, 2021). "And at the salivary level, higher levels of NLRP3 were found in cases of periodontitis compared to healthy subjects." (PMID 33802988, 2021). "Previous studies have indicated that patients with periodontitis had the increased levels of serum and salivary NLRP3 and interleukin-6 (IL-6) in comparison with healthy controls." (PMID 34645448, 2021). "The aim of this study was to investigate the non-NLRP3 inflammasome-dependent immunological response to H2S by studying PBMCs of periodontitis patients and healthy controls exposed to a H2S donor in vitro." (PMID 34408814, 2021). "Thereafter, another well‐done and extensive study used ageing‐related periodontitis as an in vivo model, suggested that NLRP3 plays an important role in osteoclastogenesis during ageing." (PMID 33382502, 2021). "The expression of NLRP3, which is involved in inflammasomes, plays a key role in periodontitis, being higher in periodontitis gingival tissues than in healthy tissues, especially at the epithelium layer." (PMID 33802988, 2021).